EML4 (EMAP like 4)
Diseases named in the same sentence as EML4 in open-access papers (continued):
Sharing a sentence is not in itself a finding about the gene and the disease.
squamous cell carcinoma (10 papers, 2010 to 2025). A carcinoma arising from squamous epithelial cells. "In the present study, we report a case of synchronous multiple primary lung cancer (MPLC) composed of two distinct pathological subtypes with epidermal growth factor receptor (EGFR) gene mutations L858R of the acinar adenocarcinoma subtype and EML4–ALK rearrangement of the squamous cell carcinoma." (PMID 32727606, 2020). "In this study, a tumor from a patient with pulmonary adenocarcinoma carrying EML4-ALK v3 unexpectedly formed squamous cell carcinoma and adenocarcinoma after inoculation into NOG mice and was finally diagnosed as pulmonary adenosquamous carcinoma." (PMID 38829559, 2024). "In the squamous carcinoma group, the main mutations were ALK (Ile1461Val) in 100% of patients and EML4 (Lys398Arg) in 75% of the patients." (PMID 36422072, 2022). "In patients with squamous cell carcinoma, the positive rate of EML4-ALK in tissue samples was 0.47%, and that in blood samples was 2.86% (P<0.05)." (PMID 32047559, 2020). "The detection of EML4-ALK by these three methods was significantly higher in patients with adenocarcinoma than in patients with squamous cell carcinoma." (PMID 32047559, 2020). "The EML4‐ALK rearrangement rate was 9.4% (107/1134), which included 100 adenocarcinomas, four squamous cell carcinomas, two adenosquamous carcinomas, and one NSCLC." (PMID 31144459, 2019). "Among all 8 EML4-ALK positive patients, two were diagnosed as squamous carcinomas, with one at the age of 46 and one at the age of 67." (PMID 25407901, 2014). "Of the 12 samples containing EML4-ALK fusions, 10 were identified as adenocarcinomas (one of which contained a mixed squamous carcinoma component), and two were identified as squamous cell carcinomas." (PMID 20624322, 2010). "Therefore, further research is needed to determine the mechanism underlying the transformation of pulmonary adenocarcinoma carrying EML4-ALK into pulmonary adenocarcinoma and squamous cell carcinoma in mice." (PMID 38829559, 2024). "Among them, EML4-ALK fusion gene was detected in 34 patients, the positive rate was 8.52% (34/399), the positive rate in adenocarcinoma was 11.62% (33/284), and the positive rate in squamous cell carcinoma was 0.86% (1/115)." (PMID 32047559, 2020). "Fifty-nine EML4-ALK-positive cases were identified, and the positive rate was 4.88% (59/1208); the positive rate was 5.84% (58/994) in adenocarcinoma and 0.47% (1/214) in squamous cell carcinoma." (PMID 32047559, 2020). "IHC was used to detect the expression of EML4-ALK in tissue samples of 2631 patients with NSCLC; 187 cases were positive, the positive rate was 7.11% (187/2631), and the positive rate in adenocarcinoma was 9.51% (170/1787) and 2.01% (17/844) in squamous cell carcinoma." (PMID 32047559, 2020).
inflammatory myofibroblastic tumor (9 papers, 2012 to 2025). A multinodular intermediate fibroblastic neoplasm that arises from soft tissue or viscera, in children and young adults. "Notably, EML4::ALK fusions are common due to inflammatory myofibroblastic tumor (IMT) occurring in the lung." (PMID 39867882, 2024). "Interestingly, ALK fusions have also been described in anaplastic lymphomas and in about 50% of inflammatory myofibroblastic tumors (IMTs) with EML4." (PMID 22363766, 2012). "Here, we described an extremely rare case of EML4::ALK positive pulmonary PLC with intestinal metastasis, which histologically mimics inflammatory myofibroblastic tumor (IMT)." (PMID 40224190, 2025).
metastatic disease (9 papers, 2013 to 2025). "Positive EGFR mutations, KRAS mutations, and EML4::ALK fusion in metastatic tumors often suggest a lung origin." (PMID 39980562, 2025). "However, some evidence showed that the presence of EML4-ALK gene rearrangement is associated with EGFR-TKIs resistance among patients with metastatic diseases." (PMID 27791985, 2017). "EML4‐ALK V3 in NSCLC is associated with a relatively poor response to ALK inhibitors and more aggressive metastatic disease than longer EML4‐ALK variants such as V1." (PMID 34661367, 2021). "The tumor in the right greater psoas muscle was identified as a metastatic tumor from the lung tumor based on ALK-positivity and the EML4-ALK fusion." (PMID 37920641, 2023). "Well-known fusion genes EML4-ALK were identified in 2 out of these 24 cases in both primary and metastatic tumours with supportive evidence from both DNA and RNA data." (PMID 26647728, 2015). "We also performed RT-PCR for the EML4-ALK gene with cDNA from all metastatic tumors and obtained the same results, that is, negative expression of the EML4-ALK gene in Cases 1, 3 and 4 (data not shown)." (PMID 23341890, 2013).
papillary thyroid cancer (7 papers, 2015 to 2026). "We describe a case of a 30-year-old man with a locally aggressive form of papillary thyroid cancer with EML4e13-ALKe20 fusion (EML4: echinoderm microtubule-associated protein-like 4; ALK: anaplastic lymphoma kinase)." (PMID 33628533, 2021). "From the patient’s papillary thyroid cancer (lymph node metastasis) we derived a primary cell line harboring an EML4-ALK gene fusion v3." (PMID 33878728, 2021). "At our institution, a patient presented with refractory papillary thyroid cancer (PTC) wherein an EML4-ALK gene fusion was detected." (PMID 33878728, 2021). "To that end, we established a novel cell line ‘JVE404’ derived from an advanced RAI-r papillary thyroid cancer (PTC) patient, harboring an EML4-ALK gene fusion variant 3 (v3)." (PMID 33878728, 2021). "Additionally, analyses of cell viability and cell-signaling protein molecules have been performed on the novel papillary thyroid cancer cell line harboring an EML4-ALK v3 derived from the patient’s tumor." (PMID 33878728, 2021).
Lung Squamous Cell Carcinoma (6 papers, 2013 to 2024). "Herein, we present the case of a 70-year-old female patient with squamous cell lung cancer harboring the echinoderm microtubule-associated protein-like 4 (EML4)-ALK fusion gene." (PMID 34324792, 2021). "They reported a 45 years old Japanese woman diagnosed as squamous cell carcinoma of lung harbored EML4-ALK gene rearrangement." (PMID 25527865, 2014). "A lung squamous cell cancer patient harboring a novel EML4-MET fusion was treated with crizotinib." (PMID 36829199, 2023). "Can we eliminate squamous cell carcinoma of the lung from testing of EML4-ALK fusiong gene?" (PMID 25527865, 2014).
lymphoma (6 papers, 2009 to 2024). A malignant (clonal) proliferation of B- lymphocytes or T- lymphocytes which involves the lymph nodes, bone marrow and/or extranodal sites. "But the report that malignant lymphoma complicated with lung adenocarcinoma harboring EML4-ALK fusion gene in one individual is rare." (PMID 25676402, 2015). "For instance, in lymphoma studies, I1171N and I1171T are reported to be AP26113-resistant, and while both appear resistant to ceritinib in NPM-ALK, they show sensitivity in EML4-ALK." (PMID 27009859, 2016).
sarcoma (6 papers, 2012 to 2025). A usually aggressive malignant neoplasm of the soft tissue or bone. "Here, we describe the case of a patient with metastatic non‐myofibroblastic sarcoma harbouring an EML4‐ALK fusion, encountering marked sequential response to alectinib and lorlatinib." (PMID 39188081, 2024). "However, molecular analysis did not detect gene fusions typical of Ewing sarcoma or CIC‐rearranged sarcoma; instead, an EML4‐ALK fusion was identified postmortem." (PMID 40904239, 2025). "In this report, we describe a case of metastatic non‐myofibroblastic sarcoma of soft tissue harbouring an EML4‐ALK fusion with dramatic clinical and radiologic response to alectinib then lorlatinib and a maintained normal quality of life of 10 months as a result of targeted therapy." (PMID 39188081, 2024). "As expected, lung tumors with driver fusions harbored mostly EML4/ALK fusions, sarcomas were driven mostly by EWSR1-related and PAX3/FOXO1 fusions, while hematologic malignancies with a spectrum of BCR/ABL1, KMT2A-related, and IGH/MYC fusions." (PMID 33889297, 2021). "Finally, HS-PSS also showed a WT status for PRC2 genes, was assigned to the provisional and not fully characterized “MPNST-like sarcoma” methylation group, was positive for SOX10, contained an almost unaltered genome proximal to 2n but harbored a translocation generating the fusion gene EML4-ALK." (PMID 36818284, 2023).
small cell lung carcinoma (6 papers, 2018 to 2025). Small cell lung cancer (SCLC) is a highly aggressive malignant neoplasm, accounting for 10-15% of lung cancer cases, characterized byrapid growth, and early metastasis. "In fact, our case is the first of small cell lung cancer with confirmed EML4-ALK mutation after surgery." (PMID 40136367, 2025). "We also included ALK-G1269A, which represents a resistant mutation reported in an EML4-ALK fusion protein in a non-small-cell-lung-cancer cases." (PMID 31334113, 2019). "An extremely rare case of small-cell lung cancer harboring variant 2 of the EML4-ALK fusion gene." (PMID 40136367, 2025). "H3122 and H2228 cell lines are non-small-cell lung cancer cell lines expressing EML4-ALK fusion protein, which are widely used in preclinical cancer research." (PMID 32344689, 2020). "We investigated an EML4-ALK-expressing human non-small-cell lung carcinoma cell line, STE-1, and a non-cancerous cell line, BEAS-2B, as a reference." (PMID 40654619, 2025).
cholangiocarcinoma (4 papers, 2018 to 2023). A carcinoma that arises from the intrahepatic biliary tree (intrahepatic cholangiocarcinoma) or from the junction, or adjacent to the junction, of the right and left hepatic ducts (hilar cholangiocarcinoma). "However, the EML4-ALK fusion gene is not specific to NSCLC, which has also been observed in many other tumors, such as IMT, pediatric rhabdomyosarcoma, high-grade pediatric glioma, ovarian cancer, and cholangiocarcinoma." (PMID 36915094, 2023).
thyroid cancer (4 papers, 2014 to 2021). "In this study, ALK targeted therapy with crizotinib and lorlatinib in a thyroid cancer patient harboring an EML4-ALK gene fusion v3, is illustrated." (PMID 33878728, 2021). "Our findings corroborate that also in thyroid cancer with EML4-ALK v3, targeting ALK appears feasible." (PMID 33878728, 2021).
adenosquamous carcinoma (3 papers, 2013 to 2023). A carcinoma composed of malignant glandular cells and malignant squamous cells. "The prevalence of the EML4-ALK fusion gene was 6.32% (6/95) among adenocarcinoma cases and 14.2% (1/7) among adenosquamous carcinoma cases." (PMID 23341890, 2013). "A previous study generated the CRISPR/Cas9-mediated EML4-ALK rearrangement in mice without notable adenosquamous carcinoma observation." (PMID 37051524, 2023).
esophageal cancer (3 papers, 2023 to 2024). A primary or metastatic malignant neoplasm involving the esophagus. "This study investigates the role of three specific proteins—FGF8, ALK, and EML4—in predicting the prognosis of patients with esophageal squamous cell carcinoma (ESCC), a common type of esophageal cancer." (PMID 39518064, 2024).
esophageal squamous cell carcinoma (3 papers, 2023 to 2024). Esophageal squamous cell carcinoma (ESCC) is a type of esophageal carcinoma (EC) that can affect any part of the esophagus, but is usually located in the upper or middle third. "The aim of this study was to examine the prognostic role of FGF8, ALK, and EML4 in esophageal squamous cell carcinoma (ESCC)." (PMID 39518064, 2024).
Ewing sarcoma (3 papers, 2017 to 2025). A small round cell tumor that lacks morphologic, immunohistochemical, and electron microscopic evidence of neuroectodermal differentiation. "An additional NSCLC line, H3122 (EML4-ALK), exhibited enhanced sensitivity to ML111 relative to Ewing’s sarcoma cells." (PMID 34683845, 2021).
fibrosarcoma (3 papers, 2020 to 2021). A malignant mesenchymal fibroblastic neoplasm affecting the soft tissue and bone. "Echinoderm Microtubule Associated Protein like-4 (EML4)-NTRK3 fusion has also been identified in infantile fibrosarcomas and congenital mesoblastic nephroma, in addition to ETV6-NTRK3 fusion." (PMID 32957984, 2020). "Genetic testing of the postmortem lung tumor and metastatic lymph node tissues revealed not only the EML4‐ALK fusion but also a previously unknown in‐frame acyl glycerol kinase to B‐rapidly accelerated fibrosarcoma (AGK‐BRAF) gene fusion." (PMID 31747139, 2020). "Three cases harbored fusions between EML4 and NTRK3, first observed in infantile fibrosarcoma." (PMID 33441414, 2021).
glioblastoma (3 papers, 2015 to 2025). The most malignant astrocytic tumor (WHO grade IV). "In the glioblastoma cell lines autophagy was induced following cannabinoid therapy (acting on cannabinoid receptors), and in crizotinib-resistant NSCLC cells, high doses (1 to 8 μM) of crizotinib were used in cells harboring a loss of EML4-ALK." (PMID 26338968, 2015).
Histiocytosis (3 papers, 2023 to 2025). An excessive number of histiocytes (tissue macrophages). "The lung nodules were diagnosed as ALK-positive histiocytosis (APH) carrying an EML4::ALK gene fusion, which microscopically displayed a mixed morphology of foamy cells, spindle cells, and Touton’s giant cells." (PMID 39867882, 2024). "Moreover, ALK-positive histiocytosis with EML4-ALK fusion in the lungs of a 52-year-old woman and a 17-year-old boy has also been reported." (PMID 36915094, 2023). "KIF5B has been shown to be the most common fusion-partner gene in ALK-positive histiocytosis, whereas CLTC, TPM3, EML4, and TFG have only been infrequently recorded." (PMID 40700600, 2025).
large cell neuroendocrine carcinoma (3 papers, 2021 to 2025). A usually aggressive carcinoma composed of large malignant cells which display neuroendocrine characteristics. "Similarly, ALK-rearranged (most commonly EML4-ALK) adenocarcinomas have been shown, albeit primarily in case reports and small series, to undergo transformation to SCLC or large-cell neuroendocrine carcinoma (LCNEC) after ALK-TKI treatment." (PMID 41516316, 2025).
lymph node metastasis (3 papers, 2016 to 2024). "Because the somatic EML4-ALK v3 rearrangement was affirmatively identified in newly acquired biopsy material from a lymph node metastasis using whole genome sequencing, the patient was considered a potential candidate for inclusion in the DRUP trial with ALK as a therapeutic target." (PMID 33878728, 2021).
medullary thyroid cancer (3 papers, 2015 to 2021). "ALK fusions have also been descried in medullary thyroid cancer (EML4-ALK and Glutamine:fructose-6-phosphate transaminase 1 (GFPT1)-ALK), with patient response to crizotinib reported in an EML4-ALK patient." (PMID 28030793, 2017).
ovarian carcinoma (3 papers, 2014 to 2025). A malignant neoplasm originating from the surface ovarian epithelium. "Targets such as HRD, BRAF, RET, HER2, and PD‐1/PD‐L1 have also emerged on the stage, but seldom research indicates that ALK inhibitors may be effective in the treatment of EML4‐ALK+ ovarian cancer." (PMID 39780907, 2025). "This may be the first clinical evidence of LGSO benefit from ALK inhibitors, to provide evidence for the use of ALK inhibitors in more ovarian cancer patients with EML4‐ALK fusion and promoting new ideas for the study of EML4‐ALK targets in ovarian cancer." (PMID 39780907, 2025). "Does it indicate that EML4‐ALK may become another potential therapeutic target for ovarian cancer?" (PMID 39780907, 2025).
pancreatic cancer (3 papers, 2021 to 2025). "Some of these fusions, like Echinoderm Microtubule-Associated Protein-Like 4 (EML4)-ALK and Striatin (STRN)-ALK, may be found in pancreatic tumors." (PMID 41374970, 2025). "EML4–ALK fusions have also been identified in other aggressive cancers, including breast, colorectal, and pancreatic cancers, albeit more rarely." (PMID 38458397, 2024). "Moreover, EML4–ALK fusions have been identified in a number of other cancers, including breast, colorectal, and pancreatic cancers, so these findings may be more widely applicable to these cancer types." (PMID 38458397, 2024).
Pleural effusion (3 papers, 2015 to 2022). The presence of an excessive amount of fluid in the pleural cavity. "The EML4-ALK rearrangement was detected in 66 samples of cell blocks from pleural effusion fluid using Ventana IHC, RT-PCR, and FISH." (PMID 25785456, 2015). "We attempted to clarify the feasibility of detecting the EML4-ALK fusion gene in pleural effusion cells using different methods." (PMID 25785456, 2015). "In this study, we collected 66 cell block samples of pleural effusion fluid from NSCLC patients and clarified the feasibility of detecting the EML4-ALK fusion in cell blocks from pleural effusion fluid with different techniques." (PMID 25785456, 2015). "Although pleural effusion is a potential candidate for molecular testing, its use in detecting EML4-ALK rearrangements has not been well investigated." (PMID 25785456, 2015).
acute myeloid leukemia (2 papers, 2018 to 2022). Acute myeloid leukemia (AML) is a group of neoplasms arising from precursor cells committed to the myeloid cell-line differentiation. "They demonstrated that many recurrent chromosomal translocations, of PML/RARα observed in Acute Promyelocytic Leukemia (APL), MLL/AF9 in Acute Myeloid Leukemia (AML), EWSR1/FLI1 in Ewing Sarcoma and EML4/ALK1 associated with lung cancer could form f-circRNAs." (PMID 30018188, 2018).
chronic lymphocytic thyroiditis (2 papers, 2021 to 2024). "Thyroid disease in the patient’s family, Hashimoto’s disease, and hypothyroidism, as well as the type of thyroidectomy, the need for indicating RAI, and smaller tumor size, clustered quite well with gene fusions related to RET, CCDC6, MET, EML4, and ALK." (PMID 39409115, 2024).
epithelioid angiosarcoma (2 papers, 2020 to 2026). "We present herein the first reported case of rare pulmonary epithelioid angiosarcoma harboring an EML4-ALK fusion, in which targeted therapy demonstrated efficacy." (PMID 41836264, 2026).
gastric cancer (2 papers, 2025). A primary or metastatic malignant neoplasm involving the stomach. "Together, these findings suggest that NEK9 may be an attractive therapeutic target for slowing or even halting the spread of certain cancers harboring EML4–ALK fusions, especially gastric cancer or NSCLC." (PMID 41154634, 2025).
gastrointestinal stromal tumor (2 papers, 2015 to 2024). "Existing literature reports that the smooth muscle differentiation of gastrointestinal stromal tumor (GIST) cells is associated with EML4::ALK." (PMID 39867882, 2024).
liposarcoma (2 papers, 2016 to 2018). A usually painless malignant tumor that arises from adipose tissue. "In our study we also noted deleterious mutations in 7 other genes (CTNNB1 (R151H), MECOM (R208C), ZNF536 (T688M), EML4 (W729L), CSMD3 (P627S), PBRM1 (N639K), PPP1R3A (C788Y)) that have also not been described previously in WD/DD liposarcoma." (PMID 29731991, 2018).
renal cell carcinoma (2 papers, 2015 to 2018). "Recently, echinoderm microtubule-associated protein-like 4 (EML4)-ALK fusion and vinculin (VCL)-ALK fusion have also been identified in non-small cell lung cancer (NSCLC) and renal cell carcinoma, respectively, which has not been described in IMT or EIMS yet." (PMID 26178751, 2015). "Some of the classical gene fusion examples involving a kinase-coding gene are EML4-ALK in lung adenocarcinoma, ALK-RET in colorectal cancers, and VCL-ALK in renal cell carcinoma (RCC)." (PMID 29455652, 2018).
thyroid (2 papers, 2016 to 2024). "MET, EML4, and ALK fusions also clustered with similar variables, along with the family history of thyroid diseases in general." (PMID 39409115, 2024).